HIF1A (hypoxia inducible factor 1 subunit alpha)
Diseases named in the same sentence as HIF1A in open-access papers (continued):
Sharing a sentence is not in itself a finding about the gene and the disease.
cancer (continued). "Treg-secreted IFN-γ drove intratumoral fragility of the remaining immune-suppressive Tregs via hypoxia-inducible factor 1-alpha (HIF1α) which stimulated host immunity to eliminate cancer cells." (PMID 33005420, 2020). "Hypoxia-inducible factor-1 alpha (HIF-1α) is a transcription factor essential for cancer cell survival, as it drives the expression of metabolism-related and survival-related genes in response to low oxygen levels." (PMID 33128030, 2020). "HIF1A dimerizes with HIF1β and activates the transcription of target genes, which exert the significant effects on cancer cell metabolic reprogramming." (PMID 32152275, 2020). "Mechanistically, hypoxia is transduced to the nucleus of cancer cells by the activation of a transcriptional program mediated by hypoxia‐inducible factor (HIF)‐1α and (HIF)‐2α (henceforth referred to as HIFα)." (PMID 32686360, 2020). "In cancer cells, hypoxia (HIF1α) and inflammatory (NFκB) pathways are tightly interconnected via prostaglandin synthesis." (PMID 32932589, 2020). "The activation of HIF-1a is generally more pronounced in aggressive tumors and can be an independent predictor of poor prognosis in certain types of cancer." (PMID 32903606, 2020). "Among HIF-1α targets relevant to malignant cancer transition, we have already pointed, herein and elsewhere, at its ability to upregulate VEGF and IGF-II." (PMID 33266015, 2020). "KEGG pathway analysis showed that cancer-related signalling pathways were enriched, including immunity, apoptosis, platinum resistance, and metabolic, hypoxia-inducible factor-1A (HIF-1A) and vascular endothelial growth factor (VEGF) signalling pathways." (PMID 32686693, 2020). "MIF has previously been described to be transcriptionally regulated by HIF-1α in cells of the trachea, lung and in cancer cells." (PMID 32885302, 2020). "In sum, our data put forward a relevant role for the GRK2/HuR/HIF1α module in cancer cells and in response to the adrenergic overdrive, regardless of the oxygen status." (PMID 32413989, 2020). "It is well known that hypoxia is a factor that promotes further cancer development due to activation of hypoxia-inducible factor 1-alpha (HIF-1α) and changes induced in the primary energy sources of the cancer cells." (PMID 33322818, 2020). "Several studies have reported the effectiveness of nanosystems containing HIF-1α siRNA to overcome drug resistance in cancer." (PMID 32974385, 2020). "HIF1α is one of key transcription factors which enhanced glycolytic genes transcription; finding the mediator who regulating HIF1α‐related glycolysis is important for exploiting effective and targeted therapies for cancer." (PMID 32291851, 2020). "Of note, a number of HIF1α inhibitors have been developed for clinical applications, mainly for the treatment of cancers, as malignant cells frequently up-regulate HIF1α." (PMID 32541026, 2020). "Hif-1α is a ubiquitous transcription factor that is involved in stoke, cancer, erythropoiesis and energy metabolism." (PMID 32876648, 2020). "Regulating the expression of HSPL1A and HIF-1α, which are involved in the stability and degradation of PrPC, effectively inhibits cancer growth and metastasis." (PMID 33276687, 2020). "HIF1α is the mRNA target of miR-155-5p which functions as defense mechanism cancer cells in Hypoxia." (PMID 32986358, 2020). "This is particularly true for a protein such as HIF1α, which has a profound influence on human cancer microenvironment (rendering model system A poorly representative of human disease), and has discordant results in the two model systems." (PMID 33077781, 2020).
cancer (continued). "Conversely, propofol prevents the activation of HIF-1α induced by isoflurane, which is related to a partial reduction of the malignant behaviour of cancer cells." (PMID 32863874, 2020). "In view of the fact that HIF-1α protein will be quickly degraded under aerobic context; it cannot act as a hypoxic-derived signal molecular to directly affect normoxic cancer cells." (PMID 32724467, 2020). "Consistently, recent studies have indicated that HIF1α increased the expression of histone demethylase KDM5B in cancer cells." (PMID 33304897, 2020). "When cancer cells lack oxygen, HIF1α is stabilized and translocated to the nucleus, where HIF1α activates angiogenesis and anaerobic metabolism." (PMID 32986358, 2020). "The role of HIF1a in human cancers is still under intensive investigation, but HIF1a has been implicated in over 60 target genes, many of which are strongly activated in tumors." (PMID 32872192, 2020). "Hypoxia-inducible factor 1-alpha (HIF1α) (overexpressed in cancer cells) is degraded by proteasomes." (PMID 32308553, 2020). "Treatment of CT26 cells with CoCl2 at different concentrations for 5 d revealed that 150 μM CoCl2 significantly upregulated HIF-1α in surviving cancer cells." (PMID 32531897, 2020). "Our analysis of large transcriptomic profiles in a broader context clarifies that HIF1A expression correlated with glycolysis score and glycolysis is positively response to hypoxia in cancer cells." (PMID 32635458, 2020). "During the fractionated and prolonged exposure of radiation, hypoxic cancer cells release master switch HIF-1α to upregulate expressions of pro-angiogenic factors AXL and VEGF." (PMID 32872195, 2020). "Elevated expression of HIF-1α, especially in renal carcinoma, promotes the colonization of cancer cells via the hyperactivation of a chemokine receptor (CXCR4) in lung parenchyma and bone marrow." (PMID 33321708, 2020). "Qian and coworkers described a prognostic role of both HIF-1α and HIF-2α isoforms for OSCC development, which was associated with an increased risk of mortality in this kind of cancer." (PMID 32846951, 2020). "The fact that severe hypoxia is a driving force for HIF-1α stabilization and metabolic reprogramming has been considered a central process in cancer development for a long time." (PMID 32846951, 2020). "In contrast, aberrant expression of STAT3, HIF1 α, NF-κB, AP-1 and FoxM1 are often observed in different types of cancers." (PMID 33053689, 2020). "In conclusion, this study shows that hemin promotes inhibition of glycolysis, glycolytic, and PPP enzyme activities and HIF-1α stabilization, which interfere with macrophage activation and their ability to eliminate cancer cells." (PMID 33187129, 2020). "Similar reports concluded that highly invasive cancer cells respond to hypoxia by the stabilization of HIF-1α, which can alter the expressions of many proteins required for invadopodium formation." (PMID 32858793, 2020). "We demonstrate that these changes result from a fibroblasts-stimulated increase in the expression of fructose bisphosphatase (Fbp) in cancer cells and the consequent modulation of Hif1α function." (PMID 31947613, 2020). "Our findings also provided new insights into the role of OA/FABP5/HIF-1α axis in the lipid-metabolism reprogramming involved in cancer cell growth in HCC." (PMID 33128030, 2020). "Although a recent study showed that AV downregulated the expression of the hypoxia-inducible factor-1α (HIF-1α) gene in cancer cell lines, the effects of AVC on hypoxic signaling has not been investigated so far." (PMID 32489686, 2020). "Oncogenic signaling pathways such as the Ras/Raf/MEK/ERK pathway and the PI3K/AKT/mTOR pathway are known to increase HIF-1α protein during normoxia by enhancing transcription and translation of HIF-1α in cancer cells." (PMID 32826949, 2020).
cancer (continued). "Under this condition with CoCl2 treatment in the two-layer co-culture system, cancer cell growth was stable, HIF-1α was upregulated in surviving cancer cells, VEGF was produced at high levels, and EC growth was enhanced." (PMID 32531897, 2020). "Of note, succinate and fumarate as metabolites derived from the TCA cycle have been described in cancer cells to block PHD activity which contributes to the stabilization of HIF-1α." (PMID 33585567, 2020). "As HIF1A is a hypoxia-stimulating factor, HIF1A-mediated regulation of a variety of genes and pathways, including angiogenesis and glycolysis, is crucial to cancer progression." (PMID 33218358, 2020). "Activated by the common cancer cell migration pathway, HIF-1α plays significant roles in EMT transcription factors." (PMID 33097763, 2020). "PGE2 has been reported to stimulate VEGF expression in human cancer cells through the activation of the HIF-1α pathway." (PMID 33050416, 2020). "As HIF-1α plays critical roles in developing resistance against other cancer therapeutics such as chemotherapy, radiotherapy, and immunotherapy, it is considered as a potential therapeutic target in cancer." (PMID 33335181, 2020). "Secondly, HIF-1α induces ectonucleoside triphosphate diphosphohydrolase 2 (ENTPD2/CD39L1) in cancer cells under hypoxia." (PMID 33027968, 2020). "A similar symbiosis occurs between cancer cells and CAFs, because also stromal cells in hypoxic areas activate the same HIF-1α-driven programs of cancer cells, i.e., they up-regulate GLUT1, glycolytic enzymes, and MCT4." (PMID 33291643, 2020). "The protein product coded by this gene, Hypoxia-Inducible Factor 1-Alpha-HIF1α, is a transcription factor, central to metabolic reprogramming in cancer and EMT-induction." (PMID 33182817, 2020). "Malignant tumors grow out of control, obstructing the oxygen supply, leading to HIF-1α overexpression, and inducing cancer cell EMT, during which E-cadherin is downregulated and Vimentin is upregulated." (PMID 33062005, 2020). "A study reports that the induction of the HCV core protein leads to stabilization and overexpression of HIF-1α in a cancer cell line and, consequently, to the stimulation of VEGF." (PMID 33135539, 2020). "Recently it was shown that hypoxia-inducible factor-1 α (HIF-1α) is targeted by apigenin in several cancers such as, ovarian cancer, prostate cancer, and lung cancer." (PMID 33195038, 2020). "Since TCGA compiles expression data from normal and cancer colon tissues, we focused our analysis in HIF1A in CD68High and CD68Low populations, in both tissues, assuming that CD68High population has a higher degree of macrophagic infiltration." (PMID 32231135, 2020). "One notable example is the known thioredoxin inhibitor Vorinostat (Zolinza), which inhibits HIF1-α and is approved for cancer treatment." (PMID 32605023, 2020). "The complex interaction between hypoxia (accompanied by the corresponding increase in Hif-1α expression) and autophagic activation has been well studied, particularly in the context of cancer progression." (PMID 33381039, 2020). "Overall, our study demonstrated the role of the JMJD2C/HIF1α/HES1 signaling axis in the miR-216b-mediated enhancement of the anti-cancer effects of cisplatin." (PMID 32972441, 2020). "Lactate promotes HIF-1α-mediated VEGF expression in the cancer cell, and expression of bFGF and VEGFR-2 by neighboring endothelial cells." (PMID 32257942, 2020). "Many factors, including EphA2, Notch4, VE‐cadherin, SLPI, TWIST, VEGF, vimentin and HIF‐1α, are related to the formation of VM in many cancers." (PMID 33118329, 2020). "ROS generated by the mitochondria in cancer cells diffuse into CAFs, inducing an increase in glycolysis regulated by upregulated HIF-1α expression." (PMID 33256814, 2020).
cancer (continued). "In renal cell carcinoma, pVHL oligomerization by PIAS4-mediated SUMOylation enhances HIF-1α stabilization to promote cancer cell migration, clonogenicity, and migration." (PMID 33273928, 2020). "ROS and NO damage DNA and modulate the activity of PARP-1, a protein largely involved in cancer progression that also regulates HIF-1α response." (PMID 32286485, 2020). "Hypoxia-related centers of necrosis are among the most important inducers of angiogenesis at relatively early stages of cancer development through the production of the hypoxia-inducible factor-1α (HIF-1α)." (PMID 32488850, 2020). "It is known that HIF-1α regulates a series of physiologic cancer pathways, such as cell proliferation, apoptosis, and angiogenesis." (PMID 33154192, 2020). "At the low doses applied in the current study, inhibition of HIF-1α has however been shown to be effective in murine cancer models where echinomycin treatment resulted in increased survival." (PMID 32529267, 2020). "Hypoxia plays a significant role in solid tumors by the increased expression of hypoxia-inducible factor-1α (HIF-1α), which is known to promote cancer invasion and metastasis." (PMID 32858793, 2020). "In this study, we identified HIF-1α as a target of regulation by BTG3 and elucidated the underlying mechanism and the implications on progression of human cancers." (PMID 33311481, 2020). "While AMPK negatively regulates both aerobic glycolysis and cellular biosynthesis, HIF-1α favors the growth advantage of cancer cells with reduced AMPK signaling." (PMID 33262773, 2020). "Elevated HIF-1α and HIF-2α levels have also been shown to be associated with poor prognosis in a number of cancers." (PMID 32571767, 2020). "HIF-1α has been shown to drive VEGF-mediated angiogenesis within the TME in a variety of cancers, including ovarian, pancreatic and breast cancers." (PMID 32316260, 2020). "We examined if the modest increase in HIF-1α in HIF-2α-KO Treg cells was sufficient to protect a host from cancer growth." (PMID 33024109, 2020). "In CRC, HIF1α expression correlates with cancer-specific mortality and reoccurrence as well as vascular invasion." (PMID 32610612, 2020). "Aberrant activation of HIF1α and related aerobic glycolysis promoted different steps of the cancer development, including GC." (PMID 32291851, 2020). "In cancer, HIF1α stabilization mediates many malignant properties, including defective angiogenesis and aerobic glycolysis, a phenotype termed the Warburg effect." (PMID 33287315, 2020). "The tumor suppressor MASPIN (SERPINB5) and SERPINE1 genes showed the highest overexpression, while the most significantly downregulated genes were HIF1A and its target genes, also involved in angiogenesis and metastasis of cancer cells." (PMID 32010430, 2020). "In hypoxic conditions, neoplastic cells have been reported to increase GLUT1 expression under the positive regulation of HIF-1α, leading to increase cellular glucose uptake, and support the aerobic glycolysis of cancer cells." (PMID 31947661, 2020). "In the current study, we have demonstrated that SETD1A promotes metabolism reprogramming through its interaction with and coactivation of HIF1α to facilitate cancer cell growth and tumorigenesis." (PMID 32291851, 2020). "It has been also shown that certain anti-cancer drugs contribute to the acquisition of the chemo-resistance through up-regulation of HIF-1α under normoxia." (PMID 32522234, 2020).
cancer (continued). "have reported that CoCl2 was used as an inducer for HIF-1α to evaluate the cytotoxic effects of ascorbate on cancer cells." (PMID 32091275, 2020). "HIF1α is commonly overexpressed in cancers, both as a result of intra-tumoral hypoxia and O2-independent upregulation by oncogenic mutations and pathways." (PMID 33077781, 2020). "At the same time, HIF-1α also upregulates the expression of glutamate receptors, thus fostering a glutamate signal in cancer cells and ultimately leading to tumor outgrowth." (PMID 32932943, 2020). "This suggests that HDAC and WDR5 can jointly epigenetically regulate the metastatic phenotype of cancer under the regulation of HIF-1α." (PMID 33109235, 2020). "It is generally accepted that HIF-1α is a central transcription factor in various cancer types including OSCC." (PMID 32846951, 2020). "Collectively, these data indicate that ALS2 expression generally coincides with the presence of HIF-1α, but that ALS2 upregulation is associated with poor prognosis in a subgroup of cancers." (PMID 33339852, 2020). "The possible relationship between Cx46/HIF-1α and the effect of Cx46 in cancer cell aggressiveness guarantees further studies." (PMID 32353936, 2020). "In response to hypoxic stress, cancer cells express HIF-1α, which plays a pivotal role in cell metabolism, proliferation, and cellular adaptation under hypoxic conditions." (PMID 33128030, 2020). "In detail, the inactivation of AMPK by genetic ablation induces the normoxic stabilization of hypoxia-inducible factor-1alpha (HIF-1α) and confers the proliferative advantages of cancer cells accompanied by the metabolic shift to aerobic glycolysis." (PMID 32050640, 2020). "The results also suggest that the FABP5/HIF-1α axis can be used to modulate lipid metabolism in cancer cells." (PMID 33128030, 2020). "Similar to the classic mechanism by which lncRNAs participate in cancer prognosis, the most common mechanism by which circRNAs regulate biological processes is also related to the HIF-1α model." (PMID 32014012, 2020). "Nevertheless, the stimulating role of HIF1α in radioresistance has been verified in various types of cancers." (PMID 33304897, 2020). "Hypoxia-inducible factor 1α (HIF-1α) is involved in the metastasis and progression of various cancers and is closely related to the failure of various cancer treatments and the resulting patient mortality." (PMID 33194655, 2020). "LW1564 significantly decreased the hypoxia-induced accumulation of HIF-1α protein in various cancer cell lines, including A549, WiDr, MIA-CaCa2, and HCT116." (PMID 33235318, 2020). "HIF-1β or Aryl hydrocarbon receptor nuclear translocator (ARNT) is constitutively expressed in most cells, but there is evidence that HIF-1α upregulates HIF-1β expression under hypoxia in some cancers." (PMID 32532126, 2020). "The role of HIF-1α in cancer development has been widely investigated as it is a key molecule for cellular adaptation in response to hypoxia, which is commonly encountered during tumorigenesis." (PMID 32847004, 2020). "Next, we investigated if the activation of ERK/HIF-1α/EMT signaling was also involved in the migration of the other types of cancer cells, such as A549 and Panc1 cells treated with XCL1." (PMID 33374849, 2020). "HIF-1α is a well-known driver of cancer cell glycolysis and uncontrolled growth that activates various oncogenic pathways." (PMID 32467667, 2020). "The HIF-1α inhibitors are mostly decreasing HIF-1α expression with a proven mRNA downregulation in the OTS preclinical models or in cancer trials." (PMID 32878021, 2020). "HIF1α has been widely considered a prominent cancer drug target due to its role in the regulation of multiple survival pathways in solid hypoxic tumors." (PMID 33128011, 2020).